IL10 (interleukin 10)
Diseases named in the same sentence as IL10 in open-access papers (continued):
Sharing a sentence is not in itself a finding about the gene and the disease.
Stroke (continued). "In a rat stroke model study, intravenous hUCBC injection induced a strong immunomodulatory reaction in the host via inhibiting splenic cytotoxic T cell release in association with an increase in anti-inflammatory IL-10 secretion and a reduction in pro-inflammatory cytokine levels." (PMID 32157146, 2020). "In addition, low levels of peripheral serum IL-10 can increase the risk of stroke." (PMID 30245755, 2018). "Furthermore, exploring the cellular mechanism underlying IL-6, IL-10 and HLA-DR release after stroke could pave the way towards preventing SAI." (PMID 27409177, 2016). "By enhancing IL-10 activity early in the post-stroke window, the immune system can be shifted across the bifurcation threshold into a favorable resolution state." (PMID 41557608, 2026). "These dynamics were captured under initial cytokine conditions of 0.1 nM (TNF-α), 0.05 nM (IL-6), and 0.01 nM (IL-10), using parameter values derived from stroke literature and cross-validated through simulation stability." (PMID 41557608, 2026). "During ischemic stroke, an increase in IL-10 expression is observed, with a peak occurring 3 days after the onset of the stroke." (PMID 40364646, 2026). "This delay, driven by cumulative exposure to TNF-α/IL-6 and implemented via a Hill function with a transcriptional lag, mirrors reported kinetics in stroke patients and experimental models, where IL-10 peaks between 36–60 hours post-insult." (PMID 41557608, 2026). "Meanwhile, IL-10, detected on microglia, and its receptor on astrocytes in experimental stroke models, enhance neuronal survival." (PMID 40362194, 2025). "Gene expression profiling revealed an upregulation of proinflammatory cytokines (TNF-α, IL-1β, IL-6) and the anti-inflammatory cytokine IL-10, particularly during the first three days post-stroke." (PMID 41373607, 2025). "The concentration of interleukins in the blood serum measured with the ELISA did not cover the profile of their gene expression in the brain tissue except IL10, which was decreased immediately after stroke." (PMID 40332314, 2025). "Based on the Western blotting results, it can be concluded that macrophage polarization in the brain following stroke primarily occurs through IL-10-mediated Stat3 signaling pathways." (PMID 40365292, 2025). "MTC has previously been reported to suppress neuroinflammation and improve neurological function in an animal model of stroke, upregulating IL‐10 and downregulating TNF‐α expression." (PMID 39960781, 2025). "Its ability to lower harmful mediators like IL-1β and IL-6 while enhancing protective factors such as IL-10 suggests a promising therapeutic strategy in stroke, traumatic brain injury, and subarachnoid hemorrhage." (PMID 40362194, 2025). "In the GluN3A KO brain three days after stroke, inflammatory factors IL-1β, IL-6, IL-10, and/or TNFα were significantly elevated, while MEM largely prevented these increases." (PMID 41369361, 2025). "Gene expression profiling showed upregulation of proinflammatory mediators (TNF-α, IL-1β, IL-6) and the anti-inflammatory cytokine IL-10, most prominently during the first three days post-stroke, with expression levels generally higher in older patients." (PMID 41373607, 2025). "In our previous studies, we demonstrated the diagnostic potential of salivary tumor necrosis factor α (TNF-α), interleukin 6 (IL-6), interleukin 10 (IL-10) and xanthine oxidase (XO) in the differential diagnosis of stroke patients." (PMID 40520895, 2025). "In stroke, IL-10 modulates the immune response by inhibiting the synthesis of pro-inflammatory cytokines (e.g., IL-1β, IL-6, TNF-α), suppressing antigen presentation, and downregulating adhesion molecules on endothelial cells." (PMID 40869247, 2025). "In our previous study, we evaluated the diagnostic potential of unstimulated and stimulated saliva in assessing TNF-α, IL-6 and IL-10 in stroke patients." (PMID 40520895, 2025).
Stroke (continued). "This dysregulation led to hyperactivated T cells, higher levels of cytokines (IL-2, IL-6, IL-10, IFN-γ), and an increased risk of stroke." (PMID 41156185, 2025). "The down-regulation of the IL10 mRNA expression was noticed in the ipsilateral hemisphere vs. the contralateral hemisphere 6 h after stroke induction (p < 0.05)." (PMID 40332314, 2025). "CRP, measurement of NLR, and interleukin-10 (IL-10) are used as predictors of functional outcomes after stroke." (PMID 40949500, 2025). "The peak in IL-10 elevation often occurs within the first 24 to 48 h after stroke onset, coinciding with the onset of neuroinflammation and the immune system’s response to injury." (PMID 40142325, 2025). "The mean concentration of IL10 decreased significantly 6 h after stroke (92.03 ± 7.83 pg/mL) in comparison to the blood serum before stroke (p < 0.01)." (PMID 40332314, 2025). "In contrast, IL-10, a key anti-inflammatory cytokine, peaks between 24 and 72 h post-stroke as part of the immune system’s counter-regulatory response." (PMID 40869247, 2025). "Regulatory B cells producing IL-10 have been shown to limit CNS inflammation and reduce infarct volume in experimental stroke models." (PMID 40356948, 2025). "Recently, regulatory T cells, identified as an immunosuppressive T cell population, have been described as a central cerebroprotective modulator after stroke, targeting multiple inflammatory pathways via the IL-10 signaling pathway." (PMID 38550345, 2024). "On the other hand, ELF-EMS upregulates anti-inflammatory cytokines like IL-10, 11, and 13 after stroke." (PMID 39553829, 2024). "TNF-α, IL-6, IL-1β, and IL-10 were also measured in peripheral blood samples to examine the possible effect of peripheral inflammatory response on the recurrent stroke." (PMID 38216560, 2024). "Studies have shown that serum levels of IL-6, IL-5, IL-10, and IL-2 in stroke patients are closely correlated with stroke prognosis." (PMID 38742047, 2024). "Patients with lower level of IL-10 have a greater possibility in developing PSD at one month after a stroke." (PMID 38421829, 2024). "Intravenous recombinant MANF treatment decreased the levels of pro-inflammatory cytokines and increased the levels of anti-inflammatory cytokine IL-10 in the infarcted cortex one-day post-stroke." (PMID 38229173, 2024). "The central nervous system (CNS) produces IL-10, which reduces the clinical symptoms of meningitis, stroke, multiple sclerosis, Alzheimer’s disease, and infection-related behavioral abnormalities." (PMID 39204168, 2024). "The polarization of IL-10-producing M2 macrophages or microglia is critical for clearing neuronal debris and minimizing brain damage after stroke." (PMID 39578419, 2024). "Studies have shown that IL-10 attenuates neuropathologic changes in stroke and multiple sclerosis and improves prognosis in mice and humans." (PMID 38550918, 2024). "The results showed that the expression of IL-10 increased after stroke, and this upregulation was more significant in the PT/S group than in the PT/NS group." (PMID 37196130, 2023). "To investigate the effect of inhibiting IL-10 expression on BBB integrity after PT stroke, we detected changes in MMP2 and MMP9 by RT-qPCR and their activity by gelatin zymography." (PMID 37196130, 2023). "B cell depletion by rituximab reduced stroke-induced hippocampal neurogenesis and cell survival, IL-10-producing B-cells limit CNS inflammation and infarct volume in experimental stroke." (PMID 38221996, 2023). "Our study demonstrated that optogenetically activated astrocytes protect BBB integrity and reduce neuronal apoptosis by upregulating IL-10, which decreases MMPs activity and ameliorates inflammation, thus providing a novel approach for stroke treatment." (PMID 37196130, 2023). "During the acute phase of stroke, interleukin-10 (IL-10) producing B cells together with T reg cells can dampen the inflammatory process and reduce infarct lesion size due to a reduced recruitment of neutrophils." (PMID 37000850, 2023).
Stroke (continued). "IL-10 were reported to be secreted by several cell types after stroke, including M2 microglia, macrophages, regulatory T cells, and B lymphocytes." (PMID 37283739, 2023). "The prognosis of ischemic stroke patients can be affected by post-stroke immunosuppression due to elevated IL-10 levels." (PMID 36793730, 2023). "Therapeutic administration of IL-10 has been shown to be neuroprotective in experimental stroke and to limit post-stroke inflammation." (PMID 36970418, 2023). "Some animal stroke experiments have reported that lymphocytosis upregulates IL-10 levels and inhibits inflammatory cytokines such as IL-6 and TNF-α, thus exerting neuroprotective effects." (PMID 37616313, 2023). "Genes involved in key signaling processes after stroke, including Il-10, Il-12, Hmgb1, Il-13, p38 MAPK, HIF1α, Stat3, and Il-4, were inhibited by NPD1 + RvD1." (PMID 37270727, 2023). "T regulatory cells and Th2 CD4+ T cells produce IL-10, the inflammatory signal after stroke; however, there are gender variations in the production of these cells." (PMID 36793730, 2023). "IL-10 has neuroprotective effect as reported in animal models of stroke with overexpression of IL-10." (PMID 36745280, 2023). "Accordingly, anti-inflammatory cytokine (TGF-beta and IL-10) results displayed that TGF-beta was decreased after the stroke at all time points and only recovered at 72-h with 12/15-LOX inhibitor." (PMID 37822799, 2023). "Lower levels of IL-10 production by cytotoxic T cells after stroke have been documented in males compared to females." (PMID 36793730, 2023). "After MCAO, animals treated with IL-10 deficient B cells exhibited larger infarct volumes, while the administration of enriched IL-10-positive B cells resulted in a reduction in ischemic infarct volume and stroke-induced splenic atrophy." (PMID 38269112, 2023). "When MSCs were added to monocytes from stroke patients, they decreased the levels of IL-1β, and increased the levels of IL-10 significantly more as compared to when they were added to monocytes from control patients." (PMID 36277912, 2022). "In experimental stroke, the levels of IL-10 mRNA and protein and IL-10R mRNA were elevated, with IL-10 observed in microglia and IL-10R on astrocytes in the ischemic penumbra." (PMID 35173738, 2022). "In one study, the neuroprotective effect of IL-10+ Bregs in a stroke model was accompanied by increased CD8+CD122+ T cells in the brain and spleen, suggesting a possible regulatory role of this cell population in the ischemic brain." (PMID 35912857, 2022). "T cells lacking Bim have a reduced production of several pro- (e.g. IL-6, IFN-γ) and anti- (e.g. IL-4, IL-10) inflammatory cytokines, which have been shown to play critical roles in stroke injury." (PMID 35149957, 2022). "For anti-inflammatory cytokines, a relatively homogenous pattern was seen; IRF5 CKO induced a significant increase in both IL-4 and IL-10 levels, and IRF4 CKO caused significant reduction in IL-4 and a decrease trend in IL-10 level, in stroke groups." (PMID 35963621, 2022). "IL-10 overreaction can lead to immunosuppression and worsening neurological prognosis after stroke, indicating that IL-10 therapy should be used with caution." (PMID 35173738, 2022). "In stroke and MS, it has been shown that IL-10 reduces neuropathology, resulting in better outcomes for mice and human." (PMID 36446955, 2022). "IL-10 has anti-inflammatory properties and is regarded as a mediator of stroke-induced immunodepression." (PMID 36430226, 2022). "Acute treatment with engineered T cells overexpressing IL-10 administered into the cisterna magna after stroke induces a switch of microglial gene expression to a profile associated with pro-regenerative functions." (PMID 36512388, 2022). "Delayed induction of anti-inflammatory IL-10 is seen post-stroke as a compensatory response, peaking within the first week." (PMID 35754983, 2022).
Stroke (continued). "In a therapeutic approach, we injected eTc-IL10 cells into the CM of WT mice 4 hr after stroke – a translationally relevant time window considering a similar time window for acute therapy with thrombolytics in stroke patients." (PMID 36512388, 2022). "The strategies to increase lymphocyte-derived IL-10 production or therapeutic IL-10 administration have been shown to improve the outcome of stroke." (PMID 36247760, 2022). "Cytokines associated with inflammation in stroke, such as IL-1, TNF-α, IL-6, TGF-β and IL-10, are released and serve as intercellular messengers." (PMID 35795571, 2022). "Strikingly, the transcription levels of multiple pro-inflammatory factors including TNF-α, IL-1β and IL-6 were significantly down-regulated and the anti-inflammatory factor IL-10 was significantly up-regulated in the stroke lesions of kaempferol-treated rats." (PMID 36293548, 2022). "Acute post-stroke treatment with engineered T cells overexpressing IL-10 modulates microglial activation and ameliorates functional deficit." (PMID 36512388, 2022). "Although some cytokines aggravate cerebral damage, other cytokines, such as interleukin-10 (IL-10), a neurotrophic cytokine containing neurons and glia, exert a neuroprotective role during stroke." (PMID 35592527, 2022). "Some animal stroke experiments have suggested that increased lymphocytes up-regulate the levels of IL-10 and inhibit the inflammatory cytokines such as IL-6 and TNF-α, thus playing a neuroprotective role." (PMID 35370926, 2022). "On the other hand, reports found not only that B cells are present in the brain post-stroke, but some subsets support recovery, including IL-10 secreting B cells (i.e., regulatory B cells; Bregs) which provide acute neuroprotection and support neurogenesis." (PMID 36446955, 2022). "Clinical and preclinical studies (mostly performed in male animals) report opposite results on the effect of IL-10 in response to stroke." (PMID 35413803, 2022). "Our results show that there is a higher release of IFN-γ and IL-10 from monocytes isolated from peripheral blood at day 5–7 after stroke compared with monocytes from healthy controls." (PMID 36277912, 2022). "Increased circulating IL-10 and decreased IFNγ concentrations correlate with the development of infection in patients after stroke." (PMID 38566903, 2022). "These deficits were even more pronounced in stroke patients who developed stroke-associated infections, with further reductions in TNF-α and increased IL-10." (PMID 38566903, 2022). "In acute ischaemic stroke, low levels of IL-10 predict worse outcomes, while exogenous administration of the cytokine improves recovery in experimental stroke." (PMID 36120102, 2022). "Overall, rPSG1-Fc appears a promising candidate stroke immunotherapy, possibly due to a strong enhancing effect on IL-10 secretion." (PMID 36120102, 2022). "The pro-inflammatory cytokines TNF-α and IL1-β were reduced in plasma from stroke animals, whereas anti-inflammatory IL-10 was elevated for 3,6′-DP." (PMID 35631536, 2022). "T regulatory (Treg) cells exhibit neuroprotective functions after stroke via the release of anti-inflammatory cytokines such as IL-10 and TGF-β." (PMID 36439129, 2022). "(F) Heatmap representation of ipsilateral brain gene expression between vehicle and eTc-IL10 treated mice 5 days after stroke; n=5 mice per condition; one sample per condition was excluded due to unsatisfactory quality control check." (PMID 36512388, 2022). "The findings identified that IL-2, IL-6, IL-10, and IFN-γ were risk factors for stroke risk in AF patients (P < 0.05)." (PMID 35600045, 2022). "Our results also indicate an anti-inflammatory profile in Cl-amidine-treated mice as shown by an increase in systemic cytokine levels of IL-10 after stroke when compared to vehicle treated ones (n=4-6; p<0.05)." (PMID 35250974, 2022). "This shift is characterized by reduced concentrations of circulating IFNγ and elevated IL-10 following stroke." (PMID 38566903, 2022).
Stroke (continued). "Lateral ventricle injection of small interfering RNA H19 reduced infarct volume and cerebral edema, decreased pro-inflammatory cytokine levels, and increased plasma anti-inflammatory cytokine interleukin-10 levels 24 h after stroke." (PMID 36275741, 2022). "Future studies should be aimed at differentiating between central and peripheral IL-10 effects post-stroke." (PMID 35173738, 2022). "In contrast, mice receiving eTc-IL10 injection in the CM had a significant improvement of functional outcome at 48 hr after stroke as shown by a reduced forelimb asymmetry in comparison to vehicle-treated mice." (PMID 36512388, 2022). "Interleukin-19 (IL-19), part of the IL-10 subfamily which includes IL-10, IL-20, IL-22, and IL-24, has been shown to be neuroprotective after stroke." (PMID 33532035, 2021). "Gut microbiota-derived SCFAs can dramatically stimulate IL-10 production from Th1 cells, which has been widely reported as a key factor in favorable stroke outcome." (PMID 34712621, 2021). "This makes it unlikely that IgA + PCs are contributing significantly to the pool of IL-10 in the stroke infarct at this chronic time point." (PMID 32956832, 2021). "Our results suggest that HIF-1α improves stroke outcomes by enhancing IL-10 levels, and curtailing iNOS, TNF-α and NF-kB levels." (PMID 34205911, 2021). "In a murine model of experimental stroke we analyzed the effects of IL-10 on the functional outcome for up to 14 days post-ischemia and defined the source of IL-10 in ischemic brains based on immunohistochemistry, flow cytometry, and bone-marrow chimeric mice." (PMID 34772416, 2021). "Consistent with increased IL-17A levels, we detected a significant upregulation of Cxcl1 and Mmp3 transcripts in the whole brain mRNA and a significant increase in absolute numbers of neutrophils at day 3 post-stroke in Il10−/− mice, respectively." (PMID 34772416, 2021). "Taken together, our data indicate a key function of IL-10 in restricting the detrimental IL-17A-signaling in stroke and further supports that IL-17A is a therapeutic opportunity for stroke treatment." (PMID 34772416, 2021). "Combined, this data suggests that the IL-10 production of infiltrating immune cells, in particular T cells and macrophages, is decisive for IL-10-mediated neuroprotection in stroke." (PMID 34772416, 2021). "Salivary TNF-α, IL-6, and IL-10 as well as TNF-α/IL-10 and IL-6/IL-10 ratio significantly distinguish stroke patients from controls with high sensitivity and specificity." (PMID 34433866, 2021). "In summary, in Wistar rats, IL-1β, IL-6, TGF-β, BDNF/TrkB and VEGF levels were increased at 24-h after stroke, IL-10 was increased at 30 days." (PMID 34408211, 2021). "The goal of this study was to analyze the role of the IL-10 signaling for the control of the detrimental IL-17A response in stroke." (PMID 34772416, 2021). "On the other hand, anti-inflammatory cytokines such as IL-10 are highly upregulated in early stroke lesions and initially down-regulated in the serum, but levels increase later on." (PMID 34966269, 2021). "Another possible mechanism lies in the protective role of regulatory lymphocytes in stroke via secreting interleukin-10 (IL-10), a critical anti-inflammatory and neuroprotective cytokine modulating post-stroke neuroinflammation." (PMID 34393983, 2021). "In stroke, IL-10 has been shown to negatively regulate proinflammatory cytokines (e.g., IFN-γ, TNF-α), and antigen-presenting cells, including microglia." (PMID 34772416, 2021). "A time-dependent increase in IL-10 as well as a decrease in TNF-α/IL-10 ratio was observed in stroke patients developing infection." (PMID 34092245, 2021). "In another report, however, antibiotic–induced dysbiosis of gut microbiota promoted anti-inflammatory cytokines IL-10 from Treg cells and simultaneously suppressed pro-inflammatory cytokine IL-17 from γδT cells, thereby improved stroke outcome." (PMID 34712621, 2021).